RAC1 (Rac family small GTPase 1)
Description:
Plasma membrane-associated small GTPase which cycles between active GTP-bound and inactive GDP-bound states. In its active state, binds to a variety of effector proteins to regulate cellular responses such as secretory processes, phagocytosis of apoptotic cells, epithelial cell polarization, neurons adhesion, migration and differentiation, and growth-factor induced formation of membrane ruffles. Rac1 p21/rho GDI heterodimer is the active component of the cytosolic factor sigma 1, which is involved in stimulation of the NADPH oxidase activity in macrophages. Essential for the SPATA13-mediated regulation of cell migration and adhesion assembly and disassembly. Stimulates PKN2 kinase activity. In concert with RAB7A, plays a role in regulating the formation of RBs (ruffled borders) in osteoclasts. In podocytes, promotes nuclear shuttling of NR3C2; this modulation is required for a proper kidney functioning. Required for atypical chemokine receptor ACKR2-induced LIMK1-PAK1-dependent phosphorylation of cofilin (CFL1) and for up-regulation of ACKR2 from endosomal compartment to cell membrane, increasing its efficiency in chemokine uptake and degradation. In neurons, is involved in dendritic spine formation and synaptic plasticity (By similarity). In hippocampal neurons, involved in spine morphogenesis and synapse formation, through local activation at synapses by guanine nucleotide exchange factors (GEFs), such as ARHGEF6/ARHGEF7/PIX. In synapses, seems to mediate the regulation of F-actin cluster formation performed by SHANK3. In neurons, plays a crucial role in regulating GABA(A) receptor synaptic stability and hence GABAergic inhibitory synaptic transmission through its role in PAK1 activation and eventually F-actin stabilization (By similarity). Required for DSG3 translocation to cell-cell junctions, DSG3-mediated organization of cortical F-actin bundles and anchoring of actin at cell junctions; via interaction with DSG3. Subunit of the phagocyte NADPH oxidase complex that mediates the transfer of electrons from cytosolic NADPH to O2 to produce the superoxide anion (O2(-)). [Isoform B]: Isoform B has an accelerated GEF-independent GDP/GTP exchange and an impaired GTP hydrolysis, which is restored partially by GTPase-activating proteins. It is able to bind to the GTPase-binding domain of PAK but not full-length PAK in a GTP-dependent manner, suggesting that the insertion does not completely abolish effector interaction.
Synonyms: MIG5; TC-25; p21-Rac1; Rac-1; MRD48
Tractability: Small molecule: a structure with a bound ligand is known; a high-quality ligand is known; it has a high-quality binding pocket. Antibody: UniProt places it where antibodies can reach, with high confidence; its Gene Ontology location is reachable by antibodies, with high confidence. PROTAC: UniProt records ubiquitination sites on it; ubiquitination databases record sites on it; its protein half-life has been measured; a small molecule that binds it is known.
Target class: Enzyme; Hydrolase
Gene: Protein-coding gene on chromosome 7 (6,374,098 to 6,403,998, forward strand). Ensembl gene ENSG00000136238.
Subcellular location: Cell membrane; Melanosome; Cytoplasm; Cell projection, lamellipodium; Cell projection, dendrite; Synapse; Nucleus; Cell projection, ruffle membrane
Subcellular location (Human Protein Atlas): Cytosol; Nucleoplasm; Nucleoli
Pathways (Reactome):
Signal Transduction: Activated NTRK2 signals through CDK5; MAPK6/MAPK4 signaling; MET activates RAP1 and RAC1; NRAGE signals death through JNK; NTRK2 activates RAC1; PCP/CE pathway; PI5P, PP2A and IER3 Regulate PI3K/AKT Signaling; PIP3 activates AKT signaling; PTK6 Regulates RHO GTPases, RAS GTPase and MAP kinases; RAC1 GTPase cycle; RHO GTPases Activate Formins; RHO GTPases Activate NADPH Oxidases; RHO GTPases Activate WASPs and WAVEs; RHO GTPases activate CIT; RHO GTPases activate IQGAPs; RHO GTPases activate KTN1; RHO GTPases activate PAKs; RHO GTPases activate PKNs; Signaling by SCF-KIT; VEGFA-VEGFR2 Pathway; VEGFR2 mediated vascular permeability
Developmental Biology: Activation of RAC1; DCC mediated attractive signaling; EPH-ephrin mediated repulsion of cells; EPHB-mediated forward signaling; Ephrin signaling; Inactivation of CDC42 and RAC1; SEMA3A-Plexin repulsion signaling by inhibiting Integrin adhesion; Sema3A PAK dependent Axon repulsion; Sema4D mediated inhibition of cell attachment and migration; Signal transduction by L1
Immune System: CD28 dependent Vav1 pathway; DAP12 signaling; FCERI mediated MAPK activation; Neutrophil degranulation; Regulation of actin dynamics for phagocytic cup formation
Disease: Constitutive Signaling by Aberrant PI3K in Cancer; FCGR3A-mediated phagocytosis; Nef and signal transduction; WNT5:FZD7-mediated leishmania damping
and 7 more pathways
Gene Ontology:
Molecular function: enzyme binding; GTP binding; GTPase activity; protein binding; protein kinase binding; protein-containing complex binding; thioesterase binding; G protein activity; Rho GDP-dissociation inhibitor binding; GTP-dependent protein binding
Biological process: actin cytoskeleton organization; actin filament organization; cell migration; cell motility; cell-matrix adhesion; hepatocyte growth factor receptor signaling pathway; lamellipodium assembly; localization within membrane; negative regulation of fibroblast migration; negative regulation of interleukin-23 production; positive regulation of bicellular tight junction assembly; positive regulation of endothelial cell migration; positive regulation of focal adhesion assembly; positive regulation of lamellipodium assembly; positive regulation of neutrophil chemotaxis; positive regulation of protein phosphorylation; positive regulation of ruffle assembly; positive regulation of stress fiber assembly; positive regulation of substrate adhesion-dependent cell spreading; regulation of cell migration; regulation of lamellipodium assembly; regulation of respiratory burst; regulation of stress fiber assembly; ruffle assembly; small GTPase-mediated signal transduction; and 40 more
Cellular component: actin filament; cell cortex; cytoplasm; cytoplasmic ribonucleoprotein granule; cytosol; extracellular exosome; focal adhesion; glutamatergic synapse; lamellipodium; melanosome; NADPH oxidase complex; nucleolus; nucleoplasm; nucleus; plasma membrane; postsynapse; recycling endosome membrane; ruffle membrane; trans-Golgi network; cytoplasmic vesicle; cytoskeleton; endoplasmic reticulum membrane; ficolin-1-rich granule membrane; membrane; secretory granule membrane; and 9 more
Genetic constraint (gnomAD): Loss-of-function variants: 1 observed, 19 expected, observed/expected ratio (o/e) 0.0526, 90% interval 0.018 to 0.25. The upper end of that interval is the gene's LOEUF score, 0.25, which puts it in group 1 of 6, group 1 being the genes least tolerant of losing a copy. Missense variants: 46 observed, 197.75 expected, observed/expected ratio (o/e) 0.23, 90% interval 0.18 to 0.3. Synonymous variants: 78 observed, 82.13 expected, observed/expected ratio (o/e) 0.95, 90% interval 0.79 to 1.15.
Gene-disease validity (ClinGen):
ClinGen rates the evidence that RAC1 causes each of these diseases.
syndromic intellectual disability (autosomal dominant): Definitive. A intellectual disability that is part of a larger syndrome.
Cancer hallmarks: invasion and metastasis (promotes); genome instability and mutations (suppresses); proliferative signalling (promotes); escaping immune response to cancer (promotes); escaping programmed cell death (promotes); angiogenesis (promotes)
Homologues: Orthologues: chimpanzee RAC1 (100% identical), dog RAC1 (100% identical), guinea pig RAC1 (100% identical), mouse Rac1 (100% identical), pig RAC1 (100% identical), tropical clawed frog rac1 (100% identical), zebrafish rac1a (98% identical), rat Rac1 (95% identical), rabbit RAC1 (94% identical), Caenorhabditis elegans rac-2 (77% identical). Paralogues in human: RAC3 (93% identical), RAC2 (90% identical), CDC42 (70% identical), RHOG (70% identical), RHOQ (65% identical), RHOJ (60% identical), RHOU (57% identical), RHOC (56% identical), RHOA (56% identical), RHOB (54% identical), RHOV (52% identical), RHOD (49% identical), and 10 more.
Diseases named in the same sentence as RAC1 in open-access papers:
RAC1 is named in the same sentence as 480 diseases in open-access papers, as found by Europe PMC text mining. Sharing a sentence is not in itself a finding about the gene and the disease. The quoted sentences say what the papers report.
breast carcinoma (356 papers, 2004 to 2026). "In contrast, another study found that ARHGAP15 immunoreactivity correlated with improved prognosis and a lower risk of recurrence in breast carcinoma tissues, possibly through Rac1 inactivation." (PMID 41373823, 2025). "This active FAK–Src complex activates Ras-related C3 botulinum toxin substrate 1 (Rac1) by recruiting and phosphorylating the p130 Cas scaffold protein (p130 Crk-associated substrate, known as breast cancer anti-estrogen resistance 1 [Bcar1])." (PMID 41155014, 2025). "Patients were divided into complete remission and recurrence (metastatic relapse) within 5 years after sampling to evaluate a possible association between RAC1 activity and breast cancer aggressiveness." (PMID 40633540, 2025). "In breast cancer, a study has demonstrated that RAC1 is associated with endocrine therapy resistance in estrogen receptor-positive breast cancer." (PMID 39898257, 2025). "Previous studies linked dysregulated RAC1 expression with tumor initiation, progression, and metastasis in cases of gastric, testicular, and breast cancers, establishing our results in COAD in line with the literature." (PMID 39201394, 2024). "The regulator of chromosome condensation 2 (RCC2) and RAS-related C3 botulinum toxin substrate 1 (Rac1) have been implicated in the promotion of breast cancer cell proliferation and migration." (PMID 39118792, 2024). "Nevertheless, Cdc42 (together with Rac1) plays a role at least in the DF variant-promoted activation of MLKL in the T-47D breast cancer cells." (PMID 39062543, 2024). "The overexpression of Rac-1 has been associated to the development of cancers such as testicular cancer, head and neck squamous cell cancer, colorectal, pancreatic, and breast cancer, and leukemia." (PMID 38362155, 2024). "As DOCK4 is a RAC1 GEF25, and RAC1 has been implicated in TEM26, we investigated the role of RAC1 in the adhesion and intercalation processes of breast cancer cells." (PMID 38762624, 2024). "It has also been reported that p120 binds to mesenchymal cadherins to activate Rac1 and increase the motility and invasiveness of the E-cadherin–deficient breast cancer cells." (PMID 39498333, 2024). "Further, active expression of RAC1 was usually linked to the promotion of metastasis and drug resistance, and it was considered a targeted cancer therapy in melanoma and breast cancer." (PMID 37999208, 2023). "Rac1 is widely known for its regulation of the actin cytoskeleton and vesicular traffic and has been implicated in breast cancer." (PMID 37444574, 2023). "Through targeting Bcl-2, CD44, and SIRT1 (silent information regulator 1), Rac1, Fra-1, Notch-1, and different cyclins, exogenous expression of miR-34a in breast cancer cells caused cell death and decreased cell proliferation and migration." (PMID 36325275, 2022). "At present, the most common type of Rac1 mutation in tumor has been reported as the Rac1b mutation, which has been identified in melanoma and breast cancer." (PMID 35031595, 2022). "In established cell lines of PDAC and breast cancer, RAC1b protein expression was strongly associated with a well-differentiated phenotype/E state in contrast to the parental RAC1 isoform." (PMID 34771704, 2021). "Similar to our finding that Rac1 is overexpressed in therapy resistant variants of breast cancer cells, Rac1 has also been shown to be overexpressed in naturally occurring lapatinib-resistant HER2 type breast cancer cell lines." (PMID 34074257, 2021). "For example, Rac1 expression is elevated in breast cancer tumours and is linked to reduced patient survival." (PMID 32915198, 2020). "Rac1 and RhoA are coordinated in breast cancer cell migration, so that Rac1 causes actin assembly at the leading edge of the cell migration and RhoA regulates cell contractility with more localized at the trailing edge." (PMID 33585411, 2020).
breast carcinoma (continued). "Rac1b, the constitutively active splice variant of Rac1, is highly expressed in colon, lung, and breast cancers, and plays a critical role in different stages of cancer progression." (PMID 32392742, 2020). "CD44 has also been linked to RhoGTPase actin cytoskeletal regulators, Rac1 and RhoA, in astrocytes as well as other systems such as breast cancer cells and keratinocytes." (PMID 33020512, 2020). "The constitutively active, GTP-bound variant of RAC1, RAC1b, is preferentially expressed in both colon and breast cancers, enhancing the downstream activation of NF-κB and the induction of cyclin D1 expression in a variety of solid tumors." (PMID 32545340, 2020). "Excess of Rac1 activity has been linked to several cancer types such as breast cancer, colorectal cancer, gastric cancer, prostate cancer, and cervical cancer." (PMID 31035701, 2019). "Rac1 is overexpressed or mutated in breast cancer and many other cancers and is linked to many other diseases." (PMID 30544910, 2018). "In order to address the prognostic implications of ARHGAP15 and Rac1 in human breast carcinoma patients, we associated the immunoreactivity of them with the clinical outcome of the patients." (PMID 29534468, 2018). "In the present study, ARHGAP15 immunoreactivity was detected in 47% of breast carcinoma cases, and was significantly associated with that of Rac1, while it was almost negligible in morphologically normal mammary epithelium." (PMID 29534468, 2018). "For example, Rac1b, a constitutively active isoform of Rac1, are overexpressed in breast carcinomas, while Rac1 and Cdc42 are associated with growth-factor-mediated proliferation, invasion, and therapeutic resistance." (PMID 29534468, 2018). "Univariate analysis showed that overexpression of β1 integrin and Rac1 was associated with breast cancer cell polarity reversal, lymph node metastasis, and poor disease-free survival in IMPC patients." (PMID 29435106, 2018). "For example, the CXCR4 ligand SDF-1 causes a significant activation of Rac1 and cell motility in breast cancer cells that depends on P-Rex1." (PMID 29983884, 2018). "For example, loss of RhoC inhibited cancer cell metastasis in a RhoC−/−; pyV-MT mouse model of mammary tumors, and knocking out one allele of the Rac1 gene impaired K-Ras-induced oral papilloma growth." (PMID 30305138, 2018). "Overexpression of a splice variant of Rac1, designated Rac1b, has also been reported in a number of tumor types, including colorectal cancer, breast cancer and lung cancer." (PMID 27442895, 2017). "For example, Rac1 overexpression has been implicated in the initiation and progression of gastric, testicular and breast cancers." (PMID 27442895, 2017). "Heregulin (HRG), a growth factor highly expressed in mammary tumors, causes the activation of P-Rex1 and Rac1 in breast cancer cells via ErbB3, leading to a motile response." (PMID 27351228, 2016). "In contrast, HACE1 deficiency results in enhanced Rac1 signaling, contributing to breast cancer progression." (PMID 27213432, 2016). "We found that HACE1 loss in mammary epithelial cells and breast cancer leads to enhanced Rac1 signaling resulting in enhanced migration, invasion and anchorage-independent growth." (PMID 25659579, 2015). "Up-regulated Rac1 promotes the invasion of B-lymphoma cells and the metastasis of breast cancer cells, whereas down-regulated Rac1 is associated with reduced E-cadherin expression and the reduced invasion of melanoma cells." (PMID 24523903, 2014). "Another study, using a Rac1 inhibitor in a retinoblastoma-deficient breast cancer cell line, demonstrated that Rac1 suppression leads to apoptosis." (PMID 25243137, 2014). "Our group has shown that elevated BCAR3 protein expression in breast cancer cells promotes c-Src/Cas interactions, c-Src kinase activity, c-Src-dependent Cas tyrosine phosphorylation, Cas/CrkII association, and Rac1 activity (and data herein)." (PMID 23762409, 2013).